NLRP3 (NLR family pyrin domain containing 3)
Diseases named in the same sentence as NLRP3 in open-access papers (continued):
Sharing a sentence is not in itself a finding about the gene and the disease.
colitis (continued). "In addition, the phenotype of disease in Rag1−/− mice receiving Nlrp3−/− or Casp-1−/− CD4+ T cells did not resemble the exacerbated colitis observed in mice receiving Asc−/− CD4+ T cells." (PMID 31379813, 2019). "In this regard, mice lacking NLRP3 exacerbated colitis in the DSS model." (PMID 31091682, 2019). "Remarkably, data are claiming that the compound MCC950 can significantly suppress the release of proinflammatory cytokines IL-1β, IL-18, and IL1-α, contribute to inflammatory effects resulting from canonical and non-canonical NLRP3 inflammasome activation in colitis." (PMID 30873162, 2019). "In addition, further studies are needed to evaluate the effects of in vivo selective blockade of non-canonical caspase-8- and caspase-11-dependent NLRP3 activation in animal models of colitis." (PMID 30559669, 2018). "In addition, unlike other CAPS-associated NLRP3 mutation, Y861F alone is not sufficient to trigger the inflammasome activation independent of signal 2, suggesting that this Tyr861 phosphorylation may regulate the NLRP3 activation specifically in some circumstances such as colitis." (PMID 30349539, 2018). "However, current pharmacological modulators of NLRP3 inflammasome tested in experimental colitis are not specific to NLRP3 inflammasome and do not inactivate both canonical and noncanonical pathways." (PMID 29872077, 2018). "Meanwhile, TER did not significantly protect the development of DSS-induced colitis in NLRP3−/− mice, suggesting that NLRP3 inflammasome may be involved in the preventive effect of TER on DSS-induced colitis." (PMID 28553294, 2017). "Therefore, we confirmed that oroxylin A could down-regulate the activation of NLRP3 inflammasome, with decreased levels of caspase-1, IL-1β and NLRP3 in colon samples of DSS-induced colitis mice." (PMID 28938606, 2017). "Thus, Nlrp3−/− CD4+ T cells (in otherwise Nlrp3-sufficient animals) produce only about 50% of IFN-γ upon activation, and this leads to uncontrolled expansion of Th17 cells in the mouse intestine in a T cell transfer model of colitis." (PMID 28149297, 2017). "Thus, we studied the role of the NLRP3 inflammasome by using an OXA-induced colitis model, a mouse UC model that is mediated by Th2 cytokines and showed the NLRP3 inflammasome has protective effects on OXA-induced colitis." (PMID 27966619, 2016). "However, there are no studies to investigate the role of the NLRP3 inflammasome in a Th2 cytokine-dominant colitis model resembling UC." (PMID 27966619, 2016). "Nonetheless, the phenotype of these knockout mice did not change after cohousing of these mice with WT mice, suggesting that the differences in gut microbes, if any, did not contribute to the high sensitivity to OXA-induced colitis in NLRP3−/− or caspase-1−/− mice." (PMID 27966619, 2016). "Unexpectedly, neither ASC nor NLRP3 played a significant role in host defense against S. Typhimurium infection, as reflected by equal bacterial counts in WT, Asc−/− and Nlrp3−/− mice at all time points, in both the typhoid and colitis models." (PMID 25115174, 2014). "Indeed, mice lacking NLRP3 have been shown to display exacerbated colonic inflammation upon DSS-induced colitis characterized by greater gut barrier damage, inflammatory immune cell infiltration, and cytokine production." (PMID 25071785, 2014). "It has to be noted, however, that this does not explain the observed differences between IFN-γ levels in the typhoid- and colitis model in Asc−/− mice and the increased hepatocellular injury inflicted upon Nlrp3−/− mice despite lower but not significantly different IFN-γ levels in the colitis model." (PMID 25115174, 2014). "Notably, there were not different in DSS-mediated colitis between lncOlfr29 -/- and NLRP3 -/- mice." (PMID 40933997, 2025).
colitis (continued). "Notably, Escherichia-Shigella also exhibited a significant positive correlation with LPS, TRAF, and NLRP3, suggesting that the ameliorative effect of ATF on the DSS-induced colitis may be partly mediated by reducing the relative abundance of Escherichia-Shigella." (PMID 40130239, 2025). "Moreover, as the possible metabolite of compound 4, coumaric acid, when combined with other anti-inflammatory compounds, could enhance the inhibitory effect on IL-1β release by NLRP3, thereby enhancing the drug’s ability to facilitate recovery from DSS-induced colitis in mice." (PMID 39202831, 2024). "In addition, the lack of NLRP3 inflammasome protects against DSS-induced colitis." (PMID 37505716, 2023). "However, it is not clear whether BUR could attenuate colitis-mediated intestinal inflammation via NLRP3 inflammasome inactivation and modulate the gut microbiota dysbiosis." (PMID 36290717, 2022). "Additionally, Rev-erbα-mediated effect of Berberine on DSS-induced colitis shows better effect when administered at ZT10 (late resting phase) compared to ZT2 (early resting phase), thus acknowledging the rationale to target core clock components in the control of NLRP3-driven diseases." (PMID 33716981, 2021). "Indeed, whilst the exact role of NLRP3 in IBD is not yet fully elucidated, increasing evidence has suggested that appropriate inflammasome activation has a protective effect in colitis and colitis-associated carcinogenesis." (PMID 33119702, 2020). "However, dextran sodium sulfate (DSS)-induced colitis could be mediated by the NLRP3 inflammasome activation-induced caspase-1 cleavage and IL-1β secretion, and mice lacking NLRP3 were significantly protected from colitis." (PMID 30696442, 2019). "Surprisingly, the NLRP3-specific inhibitor MCC950 could alleviate the DSS-induced acute colitis in mice; however, in the basis of administrating MCC950 to inhibit the activation of NLRP3, we failed to observe the protective effects of formononetin on acute colitis additionally." (PMID 29507526, 2018). "Moreover, oroxylin A did not relieve NLRP3-/- mice from the severity of colitis symptoms." (PMID 28938606, 2017). "Our results demonstrate for the first time that activating CB2R could suppress the initiation and activation of NLRP3 inflammasome by enhancing autophagy in peritoneal macrophages challenged with LPS/DSS, which contributes to the protective effect of CB2R on DSS-induced experimental colitis." (PMID 27611972, 2016). "For example, 2 groups independently reported that the absence of NLRP3 and caspase-1 attenuated chemical-induced colitis in mice, whereas other groups have reported that different inflammasome knockout (KO) mice are more sensitive to chemical-induced colitis and tumorigenesis." (PMID 26689911, 2015). "One of these agents is decursinol angelate (DA), a natural compound that was found to inhibit the activation of the NLRP3 inflammasome—without caspase-1 activation—leading to reduced pyroptosis and inflammation in the colon in DSS-induced colitis in mice." (PMID 40869366, 2025). "Both cardamonin and norisoboldine (NOR) from Tilia can alleviate TNBS-induced colitis in mice by activating AHR and eventually inhibiting the activation of colonic NLRP3 inflammatory vesicles." (PMID 37179416, 2023). "In contrast, the blockade of NLRP3 did not impact the severity of colitis, while the inhibition of mTOR resulted in the exacerbation of DSS-induced colitis in VAD mice." (PMID 37240022, 2023). "We constructed a colitis mouse model with or without a C. difficile challenge using MCC950, which is a selective NLRP3 inflammasome inhibitor, to inhibit the production of IL-1β in vivo." (PMID 36951545, 2023). "Similar to WT mice, NLRP3 KO mice also showed marked colitis after gavage of KLPJ, suggesting that NLRP3 is not involved significantly in KLPJ-mediated colitis." (PMID 36436756, 2023).
colitis (continued). "The absence of NLRP3 protected against neuroinflammatory and neurodegenerative processes in DSS-induced colitis in aged animals." (PMID 35281490, 2022). "We found that Asc−/−, but not Nlrp3−/− and Casp-1−/−, CD4+ T cells exacerbate T-cell induced colitis, suggesting that ASC in CD4+ T cells has a protective role." (PMID 31379813, 2019). "However, we believe that contributions of pro-IL-1β and pro-IL-18 downregulation to colitis are none or negligible because impact of Rev-erbα on inflammasome activation (i.e., activation of caspase-1 and maturation of IL-1β) and experimental colitis is highly Nlrp3-dependent." (PMID 30315268, 2018). "Western blotting analysis revealed that expression of the inflammasome complex proteins such as NLRP3 and ASC are not changed during colitis, but procaspase-1 is increased in its expression and cleaved into caspase-1 in DSS- and DSS+dTPP-treated mice." (PMID 23915129, 2013). "Taken together, KLPJ-mediated colitis occurs through caspase-1/11, but not NLRC4 or NLRP3." (PMID 36436756, 2023). "Inflammasome inhibitors NLRP3-IN-2, JC124, and 3,4-methylenedioxy-β-nitrostyrene (MNS) were previously reported to exert anti-inflammatory effects in various disease models but not in the dextran sulfate sodium (DSS)–induced colitis model." (PMID 35784693, 2022). "IFN-γ was shown to be significantly decreased in AOM/DSS mice models that lacked NLRP3 and caspase-1, suggesting that IFNγ could increase colon cell proliferation in primary grade DSS-induced colitis." (PMID 30447690, 2018). "Furthermore, mice lacking ASC and caspase-1 are vulnerable to DSS-induced colitis and CRC, suggesting that NLRP3 inflammasome activation may inhibit colorectal carcinogenesis." (PMID 39456655, 2024). "Based on these observations, testing MCC950 in animals with colitis (i.e., DSS, TNBS, or IL-10−/−) would allow a better characterization of the anti-inflammatory effects resulting from selective inhibition of canonical and non-canonical NLRP3 inflammasome activation." (PMID 28179906, 2017).
diabetes (590 papers, 2006 to 2026). "Its protective effects in diabetes-induced cardiac injury are therefore associated with suppression of the NLRP3 inflammasome pathway." (PMID 41399377, 2026). "Given its pivotal role in diabetes-associated inflammation, the NLRP3 inflammasome and Gasdermin D have emerged as therapeutic targets." (PMID 40427455, 2025). "Although mechanistic insights continue to evolve, the integration of SGLT2 inhibitors into AF management holds significant promise, particularly in patients with diabetes, heart failure, or obesity—conditions strongly associated with heightened NLRP3 activity." (PMID 40649732, 2025). "Dysregulated NLRP3 activation has been implicated in a variety of autoimmune and inflammatory diseases, including cryopyrin-associated periodic fever syndromes, diabetes, atherosclerosis, Alzheimer’s disease, inflammatory bowel disease, and cancer." (PMID 39816134, 2025). "The interaction between COVID-19 and comorbidities (e.g., diabetes) can improve the inflammatory response, increasing the expression of inflammatory markers such as NLRP3, ASC and caspase-1, thus elevating the risk of severe complications." (PMID 40862415, 2025). "Together, the data are consistent with a role for diabetes-induced REDD1 expression in mediating NLRP3-associated pyroptotic cell death in podocytes." (PMID 39920111, 2025). "Sterile inflammation in DN is often attributed to activation of the NOD-like receptor (NLR) family pyrin domain containing 3 (NLRP3) inflammasome complex in response to metabolic stimuli associated with diabetes." (PMID 39920111, 2025). "In exploring the effects of NLRP3 variants (such as rs4612666 and rs10754558) and T1D, a significant relationship was seen between rs10754558 polymorphism and increased risk of diabetes as well as insulin resistance." (PMID 38915451, 2024). "The NF-κB/NLRP3 axis is associated with diabetes-induced podocyte injury, contrast-induced acute kidney injury, and sepsis-induced acute kidney injury." (PMID 39698584, 2024). "Recent evidence has also shown that dysregulation of NLRP3, an inflammatory signalling molecule can cause insulin resistance and subsequently increase the risk of diabetes and CVD." (PMID 39261370, 2024). "Salidroside can significantly improve diabetes-inducedRGC pyrotosis in retina, in which, the underlying mechanism is associated with the NLRP3, NFEZL2 and NGKB1 regulation." (PMID 38243268, 2024). "In diabetes, the NLRP3 inflammasome is associated with insulin resistance and the progression of type 2 diabetes." (PMID 39220230, 2024). "Recent investigations have elucidated the pivotal role of the NLRP3 inflammasome in the inflammatory response associated with the pathogenesis of diabetes mellitus." (PMID 38510357, 2024). "The abnormal activation of Nlrp3 has been reported to be associated with several inflammatory diseases such as diabetes and Alzheimer’s disease." (PMID 39537943, 2024). "The involvement of NLRP3 inflammasome and pyroptosis has been established in cardiovascular risk factors such as hyperlipidemia, diabetes, hypertension, obesity, and HHcy." (PMID 38681198, 2024). "Obesity and diabetes are closely associated with meta-inflammation; NLRP3 is a key regulator of these inflammatory changes." (PMID 38945951, 2024). "High blood glucose and insulin resistance can lead to systemic inflammation and activate the NLRP3 pathway, which increases the risk of respiratory infections in diabetes and leads to poor infection treatment outcomes." (PMID 37868953, 2023). "It is considered that DPP-4 inhibitors prevent diabetes-induced activation of node like receptor family, pyrin domain containing 3 (NLRP3) inflammasome that causes metabolic inflammation and insulin resistance." (PMID 37305094, 2023). "Inflammatory diseases including enteritis, tumors, gout, neurodegenerative diseases, diabetes, and obesity are associated with abnormal activation of the NLRP3 inflammasome." (PMID 37300757, 2023).
diabetes (continued). "In future work, the association between the NLRP3 inflammasome and teneligliptin in diabetes-related CI will be identified by co-administering the diabetic mice with teneligliptin and the agonist of the NLRP3 inflammasome." (PMID 38127000, 2023). "In non-obese diabetic (NOD) mice, which spontaneously develop β cell autoimmunity and overt diabetes, NLRP3 deficiency results in a reduced incidence of diabetes." (PMID 37081890, 2023). "Over the past decade, it has been widely recognized that alterations in NLRP3 inflammasome activity is implicated in the pathogenesis of diabetes." (PMID 36817440, 2023). "When SGLT2 inhibitors were provided, the same group showed diabetes-associated increases in inflammation-suppressed NLRP3 inflammasome activity as well as lower mRNA levels of ASC, IL-6, IL-1b, TNF-a, and caspase-1." (PMID 37566054, 2023). "Taken together, our findings indicate that combined Yijinjing and resistance training is effective in alleviating insulin resistance and liver injury in elderly pre-diabetes, which is associated with the inhibition of NLRP3 inflammasome activity." (PMID 36817440, 2023). "Caloric restriction- and weight loss-induced insulin sensitivity was associated with decreased NLRP3 and IL-1β expression in subcutaneous adipose tissue, further suggesting that NLRP3 is associated with diabetes and obesity." (PMID 36834674, 2023). "The results showed that the expression levels of NLRP3, caspase 1, IL-1β and IL-18 were increased in CD38flox mice with diabetes compared with the normal group, whereas CD38 deficiency significantly decreased the expression of these genes at the mRNA level." (PMID 37958991, 2023). "To begin, it has been linked to diabetes-induced endothelial dysfunction, since NLRP3 knockdown in a diabetic atherosclerotic mice model led to decreased expression of adhesion molecules." (PMID 37765019, 2023). "Altogether, our results demonstrate that the protective effect of AS-IV in upregulating klotho expression in diabetes-induced podocyte injury is associated with the inhibition of NLRP3-mediated pyroptosis via the NF-κB signaling pathway." (PMID 37261217, 2023). "ROS and hyperglycemia associated with diabetes activate NLRP3 oligomerization which triggers the activation of caspase-1." (PMID 37056985, 2023). "These factors further increase the body’s blood glucose, aggravate the inflammatory response, further cause the activation of NLRP3, and finally promote the onset and progression of COVID-19 and diabetes." (PMID 37868953, 2023). "An in vitro study has indicated that NLR family pyrin domain containing 3 (NLRP3) mediated pyroptosis plays a major part in diabetes-associated periodontitis." (PMID 37275952, 2023). "NLRP3 inflammasome and its related antiviral inflammatory factors have been implicated in the pathogenesis of type 2 diabetes mellitus (T2DM) and insulin resistance, but its contribution to pre-diabetes remains poorly understood." (PMID 36248820, 2022). "This work explored the influences of BJJ in diabetes-associated AS and the potential mechanisms, notably with respect to NLRP3 inflammasome." (PMID 35692570, 2022). "Abnormal activation of NLRP3 inflammasome is pathogenic and involved in many diseases, such as hypertension, diabetes and other inflammatory diseases." (PMID 35493086, 2022). "Pyroptosis mediated by the NLRP3 inflammasome also promoted the progression of diabetes-associated nonalcoholic fatty liver disease (NAFLD) syndrome." (PMID 36387904, 2022). "NLRP3, a well-known member in inflammasomes, is essential for AS and is enhanced in aortas derived from high-risk AS patients of diabetes, smokers, hypercholesterolemia, and hypertension." (PMID 35493086, 2022). "Activation of NLRP3 inflammasome is the cause of vascular endothelial dysfunction in diabetes mellitus." (PMID 35844498, 2022). "High glucose levels can activate the NLRP3 inflammatory body, which is linked to metabolic diseases like diabetes and obesity." (PMID 36532503, 2022).